SLC7A4 (solute carrier family 7 member 4)
Description:
Involved in the transport of the cationic amino acids (arginine, lysine and ornithine).
Synonyms: CAT-4; CAT4; HCAT3; VH
Tractability: Antibody: UniProt predicts a signal peptide or a membrane-spanning region; its Gene Ontology location is reachable by antibodies, with medium confidence; the Human Protein Atlas places it where antibodies can reach. PROTAC: its protein half-life has been measured.
Gene: Protein-coding gene on chromosome 22 (21,028,718 to 21,032,933, reverse strand). Ensembl gene ENSG00000099960.
Subcellular location: Membrane
Subcellular location (Human Protein Atlas): Plasma membrane; Vesicles; Nucleoplasm
Gene Ontology:
Molecular function: L-leucine transmembrane transporter activity; basic amino acid transmembrane transporter activity; amino acid transmembrane transporter activity; transmembrane transporter activity
Biological process: L-leucine import across plasma membrane; amino acid transport; basic amino acid transmembrane transport; transmembrane transport
Cellular component: plasma membrane; membrane
Genetic constraint (gnomAD): Loss-of-function variants: 31 observed, 38.91 expected, observed/expected ratio (o/e) 0.8, 90% interval 0.6 to 1.08. The upper end of that interval is the gene's LOEUF score, 1.08, which puts it in group 4 of 6, group 1 being the genes least tolerant of losing a copy. Missense variants: 839 observed, 862.23 expected, observed/expected ratio (o/e) 0.97, 90% interval 0.92 to 1.03. Synonymous variants: 359 observed, 385.89 expected, observed/expected ratio (o/e) 0.93, 90% interval 0.85 to 1.01.
Homologues: Orthologues: chimpanzee SLC7A4 (99% identical), macaque SLC7A4 (91% identical), guinea pig SLC7A4 (83% identical), rat Slc7a4 (82% identical), mouse Slc7a4 (81% identical), rabbit SLC7A4 (80% identical), dog SLC7A4 (75% identical), pig SLC7A4 (75% identical), tropical clawed frog slc7a4 (64% identical), zebrafish slc7a4 (64% identical), Drosophila melanogaster CG7255 (38% identical), Drosophila melanogaster slif (36% identical), and 9 more. Paralogues in human: SLC7A3 (41% identical), SLC7A2 (40% identical), SLC7A1 (40% identical), SLC7A14 (39% identical), SLC7A8 (20% identical), SLC7A5 (19% identical), SLC7A11 (19% identical), SLC7A9 (19% identical), SLC7A6 (17% identical), SLC7A7 (17% identical), SLC7A10 (17% identical), SLC7A13 (15% identical).
Diseases named in the same sentence as SLC7A4 in open-access papers:
SLC7A4 is named in the same sentence as 12 diseases in open-access papers, as found by Europe PMC text mining. Sharing a sentence is not in itself a finding about the gene and the disease. The quoted sentences say what the papers report.
melanoma (2 papers, 2021 to 2022). A malignant, usually aggressive tumor composed of atypical, neoplastic melanocytes. "The results showed that melanoma tissues presented the highest expression of SLC7A4, followed by benign nevi, whereas normal skin tissues showed the lowest expression." (PMID 34458265, 2021). "Generally, the intensity of SLC7A4 staining increased with the progression of melanoma." (PMID 34458265, 2021). "Moreover, the IHC results illustrated that the expression of SLC7A4 was proportional to the progression of melanoma." (PMID 34458265, 2021). "The results demonstrated that SLC7A4 was more highly expressed in melanoma tissues than in normal skin tissues, and the relatively higher expression of SLC7A4 presented a poor prognosis in SKCM patients, indicating that it could serve as a prognostic biomarker for SKCM." (PMID 34458265, 2021).
breast carcinoma (1 paper, 2025). "Notably, only SLC7A3 and SLC7A4 showed significant associations with breast cancer patient prognosis." (PMID 38204267, 2025). "SLC7A3 is an arginine transporter, a recent study revealed that breast cancer patients with high SLC7A4 expression had better prognoses, while the role of SLC7A3 in breast cancer progression remains unclear." (PMID 38204267, 2025).
Obesity (1 paper, 2022). Accumulation of substantial excess body fat. "Seven of the genes were downregulated by obesity and reversed by VSG specific weight loss including Ido1, Aldoc, Tmem125, Dgki, Slc7a4, Msc, and Ephb3, while four were inversely regulated with obesity elevating Klhl5, Nek6, Arhgap20, and Hp." (PMID 35775614, 2022).
rhabdomyosarcoma (1 paper, 2017). A rare aggressive malignant mesenchymal neoplasm arising from skeletal muscle. "In rhabdomyosarcomas SLC7A1 and SLC7A4 were strongly expressed, with low SLC7A2 (SLC7A3 not available)." (PMID 28969007, 2017).
tumor (2 papers, 2021 to 2022). "Our results showed that SLC7A4 methylation was higher in tumor specimens than in normal tissue, and that higher SLC7A4 expression was associated with better clinical outcome." (PMID 33869043, 2021). "We speculate that SLC7A4 inhibits tumor formation in PRAD through regulation of the cell cycle." (PMID 33869043, 2021).
SLC7A4 also shares sentences with these, for which no sentence is quoted: cancer (1 paper); cardiovascular disorder (1); developmental delays (1); diabetes (1); Dystonia (1); myopathy (1); skin cutaneous melanoma (1).